MICALL1 (MICAL like 1)
Description:
Lipid-binding protein with higher affinity for phosphatidic acid, a lipid enriched in recycling endosome membranes. On endosome membranes, acts as a downstream effector of Rab proteins recruiting cytosolic proteins to regulate membrane tubulation. Involved in a late step of receptor-mediated endocytosis regulating for instance endocytosed-EGF receptor trafficking. Alternatively, regulates slow endocytic recycling of endocytosed proteins back to the plasma membrane. Also involved in cargo protein delivery to the plasma membrane. Plays a role in ciliogenesis coordination, recruits EHD1 to primary cilium where it is anchored to the centriole through interaction with tubulins. May indirectly play a role in neurite outgrowth (By similarity).
Synonyms: MIRab13; KIAA1668; MICAL-L1
Tractability: Antibody: UniProt places it where antibodies can reach, with high confidence; its Gene Ontology location is reachable by antibodies, with medium confidence. PROTAC: ubiquitination databases record sites on it; its protein half-life has been measured.
Gene: Protein-coding gene on chromosome 22 (37,905,657 to 37,942,822, forward strand). Ensembl gene ENSG00000100139.
Subcellular location: Recycling endosome membrane; Late endosome membrane; Cell projection, cilium membrane; Cytoplasm, cytoskeleton, microtubule organizing center, centrosome, centriole
Subcellular location (Human Protein Atlas): Cell Junctions; Centriolar satellite; Cytosol
Gene Ontology:
Molecular function: cadherin binding; cytoskeletal anchor activity; identical protein binding; phosphatidic acid binding; protein binding; small GTPase binding; actin filament binding; protein-macromolecule adaptor activity
Biological process: cilium assembly; endocytic recycling; endocytosis; plasma membrane tubulation; protein localization to cilium; protein localization to endosome; protein targeting to membrane; receptor-mediated endocytosis; slow endocytic recycling; actin cytoskeleton organization; cell migration involved in sprouting angiogenesis; neuron projection development; plasma membrane bounded cell projection organization
Cellular component: cell junction; centriolar satellite; centriole; cilium; cytoplasmic side of endosome membrane; cytosol; early endosome; late endosome; recycling endosome membrane; trans-Golgi network; adherens junction; plasma membrane; ciliary membrane; late endosome membrane
Genetic constraint (gnomAD): Loss-of-function variants: 61 observed, 76.81 expected, observed/expected ratio (o/e) 0.79, 90% interval 0.64 to 0.98. The upper end of that interval is the gene's LOEUF score, 0.98, which puts it in group 4 of 6, group 1 being the genes least tolerant of losing a copy. Missense variants: 1,066 observed, 1,102 expected, observed/expected ratio (o/e) 0.97, 90% interval 0.92 to 1.02. Synonymous variants: 481 observed, 456.08 expected, observed/expected ratio (o/e) 1.05, 90% interval 0.98 to 1.14.
Homologues: Orthologues: chimpanzee MICALL1 (99% identical), macaque MICALL1 (97% identical), dog MICALL1 (85% identical), pig MICALL1 (84% identical), guinea pig MICALL1 (82% identical), mouse Micall1 (78% identical), rabbit MICALL1 (75% identical), rat Micall1 (73% identical), tropical clawed frog micall1 (52% identical), zebrafish micall1a (45% identical), Drosophila melanogaster MICAL-like (29% identical). Paralogues in human: MICALL2 (32% identical), EHBP1 (18% identical), ASPM (17% identical), EHBP1L1 (16% identical), GAS2L1 (10% identical), SMTNL1 (9% identical), GAS2 (5% identical).
Diseases named in the same sentence as MICALL1 in open-access papers:
MICALL1 is named in the same sentence as 5 diseases in open-access papers, as found by Europe PMC text mining. Sharing a sentence is not in itself a finding about the gene and the disease. The quoted sentences say what the papers report.
tumor (1 paper, 2022). "In its turn, MICALL1 inhibits tumor growth through EGFR degradation." (PMID 36354672, 2022).
MICALL1 also shares sentences with these, for which no sentence is quoted: infection (4 papers); breast carcinoma (1); gastric cancer (1); ovarian carcinoma (1).